EPHX2 (epoxide hydrolase 2)
Description:
Bifunctional enzyme. The C-terminal domain has epoxide hydrolase activity and acts on epoxides (alkene oxides, oxiranes) and arene oxides. Plays a role in xenobiotic metabolism by degrading potentially toxic epoxides (By similarity). Also determines steady-state levels of physiological mediators. Bifunctional enzyme. The N-terminal domain has lipid phosphatase activity, with the highest activity towards threo-9,10-phosphonooxy-hydroxy-octadecanoic acid, followed by erythro-9,10-phosphonooxy-hydroxy-octadecanoic acid, 12-phosphonooxy-octadec-9Z-enoic acid and 12-phosphonooxy-octadec-9E-enoic acid. Has phosphatase activity toward lyso-glycerophospholipids with also some lower activity toward lysolipids of sphingolipid and isoprenoid phosphates.
Synonyms: CEH; SEH; ABHD20
Tractability: Small molecule: a drug acting on it is in phase 2 or 3 trials; a structure with a bound ligand is known; a high-quality ligand is known; it has a high-quality binding pocket; it belongs to a druggable protein family. PROTAC: ubiquitination databases record sites on it; its protein half-life has been measured; a small molecule that binds it is known.
Target class: Enzyme; Serine protease S33 family; Serine protease SC clan; Serine protease; Protease
Chemical probes: AU1235, BI-1935 (high quality), CHEMBL2392692, PD081189, PD081321, PD082289, PD082785, PD083414, PD084044, PD084310, PD084416, PD084927, PD085017, REGORAFENIB
Gene: Protein-coding gene on chromosome 8 (27,490,775 to 27,548,992, forward strand). Ensembl gene ENSG00000120915.
Subcellular location: Cytoplasm; Peroxisome
Subcellular location (Human Protein Atlas): Cytosol
Pathways (Reactome):
Metabolism: Biosynthesis of maresins; Synthesis of epoxy (EET) and dihydroxyeicosatrienoic acids (DHET)
Protein localization: Peroxisomal protein import
Gene Ontology:
Molecular function: 10-hydroxy-9-(phosphonooxy)octadecanoate phosphatase activity; epoxide hydrolase activity; lipid phosphatase activity; lysophosphatidic acid phosphatase activity; magnesium ion binding; phosphatase activity; protein homodimerization activity; toxic substance binding; catalytic activity
Biological process: cholesterol homeostasis; dephosphorylation; epoxide metabolic process; phospholipid dephosphorylation; positive regulation of gene expression; regulation of cholesterol metabolic process; stilbene catabolic process; regulation of cell growth
Cellular component: cytosol; extracellular exosome; peroxisome; peroxisomal matrix; cytoplasm
Genetic constraint (gnomAD): Loss-of-function variants: 71 observed, 79.13 expected, observed/expected ratio (o/e) 0.9, 90% interval 0.74 to 1.09. The upper end of that interval is the gene's LOEUF score, 1.09, which puts it in group 4 of 6, group 1 being the genes least tolerant of losing a copy. Missense variants: 705 observed, 706.7 expected, observed/expected ratio (o/e) 1, 90% interval 0.94 to 1.06. Synonymous variants: 251 observed, 260.23 expected, observed/expected ratio (o/e) 0.96, 90% interval 0.87 to 1.07.
Homologues: Orthologues: macaque EPHX2 (95% identical), chimpanzee EPHX2 (94% identical), dog EPHX2 (79% identical), pig EPHX2 (77% identical), mouse Ephx2 (73% identical), rat Ephx2 (67% identical), guinea pig EPHX2 (66% identical), tropical clawed frog ephx2 (55% identical), zebrafish ephx2 (50% identical), Drosophila melanogaster CG15879 (8% identical), Drosophila melanogaster CG5704 (8% identical), Caenorhabditis elegans C31H5.1 (8% identical), and 10 more. Paralogues in human: EPHX4 (21% identical), EPHX3 (19% identical), ABHD8 (16% identical), ABHD11 (13% identical), ABHD5 (12% identical), MEST (12% identical), ABHD4 (11% identical), ABHD6 (11% identical), BPHL (11% identical), SERHL2 (11% identical), ABHD14A (10% identical), ABHD14B (9% identical).
Diseases named in the same sentence as EPHX2 in open-access papers:
EPHX2 is named in the same sentence as 279 diseases in open-access papers, as found by Europe PMC text mining. Sharing a sentence is not in itself a finding about the gene and the disease. The quoted sentences say what the papers report.
Hypertension (103 papers, 2009 to 2025). The presence of chronic increased pressure in the systemic arterial system. "Dysregulation of EPHX2 has been implicated in various diseases, including renal and liver malignancies, hypertension, and hypercholesterolemia." (PMID 38297313, 2024). "K55R is an EPHX2 snp that increases sEH activity and is associated with hypertension, cardiovascular disease, and ischemic stroke in human populations." (PMID 36144230, 2022). "We aimed to assess the association of a missense mutation, R287Q, in EPHX2) gene coding for soluble epoxide hydrolase is a potential candidate in the pathogenesis of hypertension." (PMID 32181010, 2020). "Risk prediction of R287Q variant in EPHX2 gene for hypertension was also examined under additive, dominant, and recessive models of inheritance." (PMID 32181010, 2020). "Data on variants in EPHX2 gene associated with human hypertension risk are very sparse in the current medical literature." (PMID 32181010, 2020). "The aim of this case-control study was to assess the association of R287Q variant in EPHX2 gene with the protein activity of soluble epoxide hydrolase and the risk of hypertension." (PMID 32181010, 2020). "Differential transcription of four of these DEGs, which are known as associated with hypertension (F2r, Chi3l1, Ephx2, and Tlr3), was validated by qPCR." (PMID 32039698, 2019). "According to RGD annotations, there were several genes related to CNS diseases (Abcg2, Ephx2, RGD1563482, Tgfb2, Mal, and Cst3), and 3 genes associated with hypertension (Ephx2, Cst3, and Ltbp2) are found on this list." (PMID 26822062, 2016). "Analysis by using two models of programmed hypertension indicated Ephx2 expression and SEH (encoded by Ephx2) activity played a direct role in renal programming." (PMID 27897982, 2016). "All this and the increased transcription of Ephx2 found earlier in hypothalamus and renal cortex of ISIAH rats prompt us to consider Ephx2 as a key candidate for further studies of the mechanisms underlying the stress-sensitive hypertension in ISIAH rats." (PMID 28105926, 2016). "Two DEGs associated with hypertension (Ephx2 and Glp1r) were in the list of the top 40 genes showing the highest differences in expression in ISIAH and WAG renal cortex." (PMID 26821914, 2016). "The list of the top 40 genes showing the highest differences in expression in ISIAH and WAG renal cortex contained two genes (Ephx2 and Glp1r) associated with hypertension." (PMID 26821914, 2016). "In the current study, Ephx2 was one of the DEGs associated with hypertension and showing the highest differences in expression in ISIAH and WAG renal medulla." (PMID 28105926, 2016). "In the current study, only 3 genes associated with hypertension (Ephx2, Cst3 and Ltbp2) appeared on the list of the top 40 DEGs that make the largest contribution to inter-strain differences." (PMID 26822062, 2016). "The association with incident CHD should have been confirmed and a potential correlation of the EPHX2 K55R variant to an increased risk of hypertension was analysed." (PMID 19814804, 2009). "The present study confirmed the positive association between EPHX2 gene R287Q mutation and reduced hypertension risk in a Han Chinese population, and extending previous findings, we noted that this association was more obvious under the dominant model of inheritance." (PMID 32181010, 2020). "It is hence reasonable to hypothesize that variation in EPHX2 gene may be predictive of hypertension risk." (PMID 32181010, 2020). "Fourthly, only an exonic variant in EPHX2 gene was genotyped in this study, and it is of added interest to incorporate more variants in this gene to further interrogate haplotype-based contribution to hypertension risk." (PMID 32181010, 2020).
Hypertension (continued). "The discussion of ten of them known as associated with hypertension demonstrated that four of these genes (Avpr1a, Hsd11b2, Agt, Ephx2) may provoke the hypertension development, and Mpo may contribute to insulin resistance and inflammation in ISIAH rats." (PMID 28105924, 2016). "In the current study, we defined 3 genes associated with hypertension (Ephx2, Cst3 and Ltbp2) that might be of interest for further studies as potential therapeutic targets for stress-sensitive hypertension therapies." (PMID 26822062, 2016). "Of the top 40 DEGs making the greatest contribution to the interstrain differences, there were 3 genes (Ephx2, Cst3 and Ltbp2) associated with hypertension that were considered to be suitable for further studies as potential targets for the stress-sensitive hypertension therapy." (PMID 26822062, 2016). "Moreover, in the spontaneously hypertensive heart failure rat, an inbred, genetically homogenous model that mirrors human hypertension-associated heart failure, an alteration of the gene encoding sEH (Ephx2) facilitated CHF progression and was identified as a heart failure susceptibility gene." (PMID 30728778, 2019). "The dysregulation of EPHX2 was connected to hypertension, hypercholesterolemia, cardiovascular diseases, and hepatocellular carcinoma." (PMID 41465541, 2025). "The rs751141 polymorphism of Ephx2, which reduces the hydrolase activity of sEH, has been shown to be protective against essential hypertension in humans." (PMID 35682911, 2022). "This point is best illustrated by the ability of EPHX2 inhibitors to shift both hypertension and hypotension toward normotension in rodent models." (PMID 34342583, 2021). "Epoxide hydrolase 2 (EPHX2) gene coding for soluble epoxide hydrolase is a potential candidate in the pathogenesis of hypertension." (PMID 32181010, 2020). "Further investigations in other ethnic or racial populations are needed to confirm the findings of this study and examine molecular mechanisms of EPHX2 gene and hypertension." (PMID 32181010, 2020). "Evidence is growing indicating that epoxide hydrolase 2 (EPHX2) gene coding for soluble epoxide hydrolase is a potential candidate in the pathogenesis of hypertension." (PMID 32181010, 2020). "In rodent models, sEH inhibition or genetic deletion of EPHX2 attenuates renal damage due to hypertension, salt-sensitive hypertension, diabetes, and IR injury." (PMID 28552948, 2017). "Altogether, we found nine genes (Cst3, Cyp11b2, Ephx2, Fn1, Igfbp2, P2rx4, Prkcd, RT1-Ba, and Sult1a1) annotated in the RGD as associated with hypertension in this group." (PMID 26822062, 2016). "Among them, Avpr1a, Ephx2, Hba2, Hba-a2, and Npy1r have been identified as differentially expressed genes in the kidney in a variety of programmed hypertension models." (PMID 27918455, 2016). "Ephx2 was also considered to be one of the gatekeeper genes that contributes to programmed hypertension." (PMID 26822062, 2016). "Since several studies revealed an influence of EPHX2 gene expression on blood pressure by alterations in EET levels, the association of the K55R variant with increased risk of hypertension was investigated." (PMID 19814804, 2009). "The decrease in enzyme activity of EPHX2 has been involved in hypertension and preeclampsia." (PMID 38666947, 2024). "Moreover, blocking EPHX2 was accompanied by a significant improvement of hypertension and endothelial function." (PMID 34040693, 2021). "We provide evidence that R287Q mutation in EPHX2 gene was associated with reduced risk of primary hypertension and low activity of soluble epoxide hydrolase.EPHX2) gene coding for soluble epoxide hydrolase is a potential candidate in the pathogenesis of hypertension." (PMID 32181010, 2020).
Hypertension (continued). "Animal studies showed that soluble epoxide hydrolase inhibitor, 12-(3-adamantan-1-y1-ureido)-do-decanoic acid (AUDA), was found to attenuate angiotensin II-induced hypertension, and EPHX2 knockout mice exhibited lowered blood pressure and were immune from ventricular dysfunction." (PMID 32181010, 2020). "The well-known role of Ephx2 is the regulation of hypertension in the kidney." (PMID 32344531, 2020). "Ephx2 was also recognized as a gatekeeper gene contributing to programmed hypertension." (PMID 28105926, 2016). "One of these genes, Ephx2, was already proposed as a target for the treatment of hypertension." (PMID 26822062, 2016). "Four of them (Avpr1a, Hsd11b2, Agt, Ephx2) may provoke the hypertension development, and Mpo may contribute to insulin resistance and inflammation in the ISIAH rats." (PMID 28105924, 2016). "Furthermore, a significantly increased expression of gene Ephx2 (soluble epoxide hydrolase) was noted in both genetic and acquired animal models of hypertension." (PMID 26712746, 2015). "Hence, in the three models of hypertension, two programmed by maternal stress and one genetic, Ephx2 gene expression and SEH activity seem to play a direct and indirect role." (PMID 26712746, 2015). "Given that arachidonic acids are ligands for PPARs, that the Ephx2 is a PPAR target gene, and that increased expression/activity of sEH have been associated with hypertension, these observations implicate a role of PPAR signaling pathway for high-fructose-induced programmed hypertension." (PMID 26712739, 2015). "Furthermore, inhibition of EPHX2 might have pleiotropic beneficial effects on hypertension, endothelial dysfunction, OS, and CV disease." (PMID 34040693, 2021). "It is noteworthy that Ephx2 gene expression and SEH activity seem to play a crucial role in a variety of programmed hypertension models." (PMID 27918455, 2016). "Moreover, we studied the distribution of genotypic and allelic frequencies of the EPHX2 K55R polymorphism in CHD patients and controls in order to confirm the association of this genetic variant with incident CHD and to analyse a potential correlation with increased risk of hypertension." (PMID 19814804, 2009). "Numerous studies in animal models and cell lines have reported the involvement of EPHX2 in a variety of metabolic diseases, including cardiovascular diseases (CVD), hypertension, Non-alcoholic fatty liver disease (NAFLD), and diabetes, highlighting the potential benefits of its inhibition." (PMID 32192153, 2020).
diabetes (49 papers, 2012 to 2026). "In related research, hypertension- and diabetes-associated ischemic stroke risk increased through the EPHX2 gene variants in the Turkish population." (PMID 35563342, 2022). "Large epidemiologic studies (the Atherosclerosis Risk in Communities and the Diabetes Heart Study) reported that rs7837347, rs7003694, rs747276, and rs41507953 EPHX2 gene polymorphisms were associated with subclinical CV disease and coronary heart disease." (PMID 34040693, 2021). "Using the HFD model, we show that pre-diabetes causes increased EPHX2 gene expression as well as increased sEH protein expression in brain." (PMID 24824753, 2014). "A study on the relationship between EPHX2 Arg287Gln and DN in Chinese patients with type 2 diabetes mellitus showed that there was a significant correlation between Arg287Gln and homocysteine (Hcy) levels and DN risk." (PMID 38425758, 2024). "EPHX2 plays further roles in glucose homeostasis, obesity, and diabetes, as shown in rodent and cell-line models." (PMID 32192153, 2020). "The locus on chromosome B1, common to both analyses, revealed coding and splice region variants in candidate genes, ANK1, EPHX2 and LOX2, implicated in diabetes mellitus and lipid dysregulation." (PMID 33154479, 2020). "This discrepancy indicates that factors such as ethnicity, diabetes, obesity, and environment affect the activity of EPHX2 in humans." (PMID 32192153, 2020). "Given the potential involvement of EPHX2 in obesity and diabetes, we hypothesize that EPHX2 levels in obese humans are elevated over those of normal-weight individuals." (PMID 32192153, 2020). "Ephx2-/- mice with streptozotocin-induced diabetes showed an increase in the rate of epithelial wound healing, decreased sensory nerve degeneration of corneas, and did not develop diabetes-associated dry eye symptoms." (PMID 30792659, 2019). "We have previously demonstrated that pre-diabetes insulin resistance leading to DM2 upregulates the EPHX2 gene which codes for sEH and consequently increases sEH content in mouse brain." (PMID 34063817, 2021). "Furthermore, the increased expression and activity of EPHX2 results in decreased EET levels and thus the EPHX2/EET pathway contributes to obesity and diabetes-induced endothelial dysfunction and cardiovascular disease." (PMID 32192153, 2020). "Moreover, whether regular exercise affects EPHX2 expression or circulating EET levels in obesity and diabetes is still elusive." (PMID 32192153, 2020). "We observed a significantly elevated expression of EPHX2 and ER stress markers in both the SAT and PBMCs of obese individuals without diabetes as compared to normal-weight individuals." (PMID 32192153, 2020).
Obesity (34 papers, 2012 to 2025). Accumulation of substantial excess body fat. "EPHX2, a gene implicated in oxidative stress responses, shows elevated expression in metabolic disorders such as obesity at both transcriptional and translational levels." (PMID 40150366, 2025). "The variant EPHX2(R287Q) is associated with an increased risk of obesity and coronary artery calcification in humans." (PMID 32192153, 2020). "As another approach to elucidate a potential causative role for specific oxylipins in SO-induced obesity, we treated WT mice on the soybean oil diet with an inhibitor of EPHX2 (sEHI) in the drinking water for 16 weeks and analyzed the oxylipin levels in the liver." (PMID 41167395, 2025). "In addition, this increase strongly correlated with adiposity markers (BMI, waist, hip, and PBF), confirming the association between EPHX2 expression and obesity in humans, as observed in mouse models of obesity." (PMID 32192153, 2020). "Notably, EPHX2 genetic deficiency or pharmacological inhibition have been shown to attenuate diet-induced ER stress in the liver and adipose tissue of rodents and to suppress colonic inflammation induced by obesity." (PMID 32192153, 2020). "Here, we observed a correlation between obesity and the expression levels of the pro-inflammatory enzyme EPHX2 in adipose tissue and PBMCs in humans, findings supported by our in vivo results." (PMID 32192153, 2020). "While the expression of EPHX2 is normally lower in adipose tissue than in liver or kidney, increased EPHX2 expression and activity were observed in a high-fat-diet-induced mouse model of obesity and during differentiation of murine adipocytes." (PMID 32192153, 2020). "Nevertheless, the functional contribution of EPHX2 and its anti-inflammatory substrates to human obesity remains poorly understood." (PMID 32192153, 2020). "To elucidate the role of EPHX2 in obesity, we assessed its expression levels in PBMCs and SAT in normal-weight and obese individuals before and after exercise." (PMID 32192153, 2020). "The contribution of EPHX2 activity to human obesity remains unexplored." (PMID 32192153, 2020). "Our finding further supports the key role of EPHX2 expression and activity in decreasing EET levels; thus, their anti-inflammatory benefits in mature adipocytes as well as in obesity and its related metaflammation." (PMID 32192153, 2020). "This increase was not linked to changes in hepatic mRNA levels of EPHX1 and EPHX2 as both microsomal and soluble isoforms' expression were not significantly altered with T2DM in patients with obesity." (PMID 38677183, 2024).